CDK6 (cyclin dependent kinase 6)
Diseases named in the same sentence as CDK6 in open-access papers (continued):
Sharing a sentence is not in itself a finding about the gene and the disease.
tumor (continued). "The expression level of cell cycle‐related proteins, such as cyclin D1, cyclin E, Cdk2, Cdk4, Cdk6, and PCNA was also decreased in anti‐Chi3L1 antibody‐treated lung metastasis tumor tissue." (PMID 34861103, 2022). "Combining tumor-normal and inter-tumor analyses, we identified overexpressed targets including PDGFRB, FGFR4, ERBB2/3, CDK6 kinases and MFAP5, HMCN1, and Hsp proteins in HCC, many of which showed low frequencies of genomic and/or transcriptomic aberrations." (PMID 35433463, 2022). "Of the primary tumour biopsies, 22.7% of the tumours were positive for both Rb and CDK4, 52.9% were positive for Rb and CDK6, and 43.1% was positive for Rb, and CDK4 or CDK6." (PMID 34921235, 2022). "A tissue microarray analysis of 109 primary tumour biopsies revealed a subset of patients (20–23%) with intact Rb, but defective p16 or overexpression of CDK4 and/or CDK6." (PMID 34921235, 2022). "Consistently with transcriptomic analysis, we also observed marked differences in the mRNA levels of BAX, HRK, CDK6, CDK14, and BCL2 between the sgCONT and NOXAKO tumor cells after co-incubated with CD19 CAR T cells." (PMID 35370290, 2022). "The downregulation or inhibition of CDK6 or CDK 4 induces cellular apoptosis, suppresses tumor proliferation, migration, and invasion." (PMID 35459184, 2022). "In KB-C2-k.o.cdk6-bearing nude mice with DOX treatment, the tumor cells that had invaded in the interior of the organ were the least, and for the lungs, they were detected only around one outside and no apparent signals were detected inside the lung tissues." (PMID 35459184, 2022). "To date, most of the studies have been done investigating the effects of miR-34 in NSCLC treatment due to its activity as a master tumor suppressor by silencing its multiple targets (e.g. CDK4, CDK6) involved in cell cycle regulation." (PMID 36303933, 2022). "Expression of WEE1 (P = .006), CDK6 (P = .02), and CDK7 (P < .001) was enriched in the squamous subtype in both PDCLs and bulk tumor." (PMID 33039466, 2021). "Gene expression analysis of MSL tumours showed that they retained RB1 while displaying significantly lower CDK4 and CDK6 expression levels, which means they have a pre-set level for reduced cell cycle progression." (PMID 34316709, 2021). "We found that CDK2, CDK4, CDK6, and STAT3 expressions were higher in tumor cohorts compared to normal cohorts." (PMID 33668805, 2021). "propose that CDK4 regulates prometastatic inflammatory cytokine signaling, whereas CDK6 mainly controls DNA replication and repair processes, indicating that CDK4 and CDK6 facilitate tumor growth and progression in multiple cancers." (PMID 35095879, 2021). "Immunohistochemistry staining of the tumor tissues showed significantly reduced expressions of Rb, CDK2, CDK4, and CDK6 in vanoxerinedihydrochloride treatment group, as compared to control PBS treatment group." (PMID 33579185, 2021). "The potency of CDKN2B/p15INK4B in tumor suppression relies on its strong binding via key N-terminal residues to and inhibition of CDK4/CDK6." (PMID 33824349, 2021). "The expanding clinical application of CDK4- and CDK6-inhibiting drugs in the management of hormone-sensitive breast cancer has raised a great interest in also testing these G1/S cell-cycle blocking agents in other neoplasms, for which the potential clinical benefit is still largely unknown." (PMID 34445095, 2021). "p16ink4a exerts tumor suppressive function by inhibiting the activities of the cyclin D-dependent kinases, CDK4 and CDK6, and preventing the retinoblastoma protein (Rb) phosphorylation and dissociation from the transcription factor E2F1." (PMID 34277422, 2021). "Immunohistochemistry staining of tumor tissues showed that aminoquinol treatment significantly reduced the expressions of Rb, CDK4, CDK6, PI3K, pho-AKT and pho-mTOR, as compared to the control group." (PMID 34335258, 2021).
tumor (continued). "Clear evidence does exist that tumor cells exposed to CCND1/CDK4 and CDK6 complex inhibitor increase their sensitivity to IR thanks to the induction of sustained DNA double-strand breaks (DSB)." (PMID 34445095, 2021). "Among them, cyclin-dependent kinase 6 (CDK6) and ZEB1/ZEB2 were essential regulators in cell cycle and metastasis of tumor cells, respectively." (PMID 34796112, 2021). "As CDK6 plays an important role in T cell development and CDK4/6 inhibitors boost T cell-mediated anti-tumor immunity, we here aimed to delineate T cell-intrinsic functions of CDK6 focusing on peripheral CD8+ T cells." (PMID 34248938, 2021). "We analyzed and visualized the relationship between four kinds of mRNAs (SNCG, PGD, CDK6, and GCC1) and tumor purity and immune cell infiltration using the TIMER tool." (PMID 34615480, 2021). "Our analyses identified drugs targeting CDK4, CDK6 and AURKA as strong candidates for MB; all of these genes are well validated as drug targets in other tumour types." (PMID 34154646, 2021). "The anti-proliferative effects of Clo and Fenti occur also in 3D cancer models (i.e., tumor spheroids) and in a synergic manner with the CDK4/CDK6 inhibitors palbociclib and abemaciclib." (PMID 33805656, 2021). "The p16 was widely known as a tumor suppressor inhibiting the CDK4 and CDK6, impeding the process from G1 to S phase." (PMID 32628820, 2020). "The analysis of CCA tumor samples employing TCGA database indicated CDK4 and CDK6 overexpression versus normal samples." (PMID 33116269, 2020). "Thus, the presence of p16INK4a determines whether CDK6 acts as a tumor-suppressor." (PMID 33255177, 2020). "TCGA dataset mining was performed using UALCAN to shown that abnormal expression of the hub genes, including CDK1, VEGFA, PRDM10, RUNX1, CDK6, HSP90AA1, and MYC, were significantly up-regulated between ESCA primary tumor and normal tissues." (PMID 32662828, 2020). "The CDK4 and CDK6 overexpression and copy number gain in CCA tumor samples further suggest potential sensitivity of CCA to palbociclib treatment." (PMID 33116269, 2020). "Roniciclib binds to and inhibits the activity of CDK1/Cyclin B, CDK2/Cyclin E, CDK4/Cyclin D1, CDK6/Cyclin D3, and CDK9/Cyclin T1, which are serine/threonine kinases playing key roles in the regulation of tumor cell proliferation and survival." (PMID 32737364, 2020). "Elevated expression of PCAT-1 negative regulates p27/CDK6 expression by inducing G0/G1 cell cycle arrest through AMPK augmentation, contributing to a tumor-promoting status." (PMID 32754302, 2020). "As a result, cyclin dependent kinase 6 (CDK6) and ras homolog family member U (RHOU) have been identified as potent biomarkers for predicting the tumor invasiveness in patients with NF-PitNET." (PMID 32498309, 2020). "CCT020312 suppressed tumor growth and reduced the protein levels of CDK4 and CDK6 in MDA-MB-453 xenograft mice." (PMID 32508655, 2020). "Aberrant expression of PCAT-1 in the tumor microenvironment triggers fibroblast differentiation which negative regulates p27/CDK6 by inducing G0/G1 cell cycle arrest and AMPK augmentation, contributing to a tumor-favoring metabolic status." (PMID 32754302, 2020). "Most of these genes (STAT5B, CDK6, CDK2, CDKN1B, E2F8, and E2F1) showed high mRNA expression in tumor tissues compared to adjacent non-tumor tissues." (PMID 32807134, 2020). "The results of immunohistochemistry revealed that overexpression of CASC21 resulted in an increase in the expression of CDK6 in mouse tumor-bearing tissues, and knockdown of CASC21 resulted in a decrease in the expression of CDK6 in tumor-bearing tissues." (PMID 32584787, 2020).
tumor (continued). "To validate the results from RNAseq, we measured expression of six genes (COL1A1, FN1, MMP2, TFPI2, CDK6, and CDK4) that were significantly up-regulated in tumor cells compared to normal epithelium by RT-qPCR." (PMID 33142242, 2020). "We analyzed CDK4, CDK6, cyclin A, cyclin D1, ATF4, and CHOP protein levels in excised tumor sections from saline- and CPX-treated groups." (PMID 32719342, 2020). "Mechanistically, we identified that a tumor suppressor, miR-627-5p targeted CDK6 at its 3’UTR and palbociclib treatment led to an increased level of this tumor suppressor." (PMID 31462285, 2019). "The expression levels of CDK6 and EGFR were further observed in GC and their matched adjacent non-tumor tissues of 40 patients by immunohistochemical staining followed by the correlation analysis of the expression levels of the two proteins and miR-1296-5p." (PMID 30530570, 2019). "Other tumour samples showed expression of CDK4, CDK6, and p-Rb protein but also p16 expression, which is associated with ineffectiveness of palbociclib, and these patients were therefore regarded as potential nonresponders." (PMID 30804704, 2019). "To verify that UCA1 regulate EZH2 and CDK6 expression through sponging miR-26a and miR-26b, we first quantified the EZH2 and CDK6 protein level in tumour and control tissues by immunoblotting." (PMID 31272462, 2019). "CDK6 and MAGI2-AS3 in CSCC and non-tumor tissues collected from 64 CSCC patients were first detected by RT-qPCR." (PMID 31832086, 2019). "Further stratified by tumour site, we report that primary tumours (n=80) were positive for CDK4 in 60.0%, for CDK6 in 85.0%, for p-Rb in 60.0%, and ≤10% for p16 in 37.5%." (PMID 30804704, 2019). "It was observed that levels of CDK6 and MAGI2-AS3 expressions were significantly higher in CSCC tissues comparing to non-tumor tissues (p < 0.05)." (PMID 31832086, 2019). "However, in ER-negative cells where PPM1A expression is low, CDKs are not dephosphorylated, and the phosphorylated form of CDK6 phosphorylates RB, which causes the release of E2F, allowing it to bind DNA and induce transcription of E2F-regulated genes, ultimately stimulating tumor growth." (PMID 31372497, 2019). "(iv) PPM1A was a member of the protein phosphatase 2C family and an important tumor suppressor, which was involved in regulation of multiple pathways, such as TGFβ/Smad, JNK/p38, Cdk2, Cdk6, and Akt/ERK signaling." (PMID 31920959, 2019). "Whereas we found pronounced tumor angiogenesis in control tumors, de novo blood vessel formation when analysed by CD31 staining was strongly reduced in the CDK4 and CDK6 knockdown residual tumors." (PMID 30858922, 2019). "Western blot data showed that the protein levels of PCNA, CDK4, CDK6, Cyclin D1, MMP-2, MMP-9, and Bcl-2 were decreased, but cleaved caspase-3 was increased in tumor tissues of ApoE KO mice compared to those of WT mice." (PMID 31275318, 2019). "Silencing of circHIPK3 decreased the proliferative and survival capacities, induced apoptosis of gallbladder cancer cells through sponging the tumor-suppressive miR-124, and increased expression of ROCK1 and CDK6, which are miR-124 targets." (PMID 30999909, 2019). "A small proportion of initial tumours had SNVs in the G-protein gene, GNAS (5%; 2/38), IDH1/2 (5%; 2/38), and the Rb-specific cell-cycle regulation genes CDK6 and RB1 (5%; 2/38)." (PMID 32082376, 2019). "It has been also demonstrated that the normal function of this tumor suppressor miRNA is to down-regulate a number of putative oncogenes including validated miR-22 targets MAX, MYCBP, HDAC4, HDAC6, CDK6, CDKN1A and NCoA1." (PMID 29716630, 2018). "Many studies focusing on the oncogenic functions of c-Fos have demonstrated its involvement in tumor growth through the modulation of Cyclin D1, which is a nuclear regulatory subunit of the cyclin-dependent kinases (CDK)-4 and CDK-6." (PMID 30423928, 2018).
tumor (continued). "Another miRNA epigenetically silenced in both solid and hematological malignancies is the miR-124 family (miR-124-1, miR-124-2, and miR-124-3), a tumor suppressor miRNA, which targets RAC1 and cyclin-dependent kinase 6 (CDK6)." (PMID 29419779, 2018). "Among the overlapping genes, we extracted CDK2, CDK6, and EGFR, which are all known to promote tumor cell growth." (PMID 29540837, 2018). "In the present study, we also found that the overexpression of CDK6 in human HCC tissues was due and correlated to the overexpression of a circulating RNA, circ-ZEB1.33, not only in the tumor, but also in the serum." (PMID 30123094, 2018). "There are a further eight tumor-suppressor genes (DLEU2, CDKN2C, SPRY4, UBE2QL1, LIN9, TFPI2, LRIG3, DUSP1) and six genes serve as both oncogenes and tumor-suppressor genes (FOXO1, CAV1, KLF6, CDK6, PLK1, CTGF)." (PMID 30563222, 2018). "It has now been well established that the RB tumor suppressor is a primary target of CDK4 and CDK6 kinases." (PMID 30701029, 2018). "In summary, circ-ZEB1.33 is a tumor promotion circular RNA, promoting HCC cell proliferation by enhancing the expression of CDK6 through sponging miR-200a-3p." (PMID 30123094, 2018). "Proliferation promotion roles of the circ-ZEB1.33-miR-200a-3p-CDK6 regulating axis are existed and verified in human HCC, both tumor and serum circ-ZEB1.33 can serve as an indicator for the prognosis of HCC patients." (PMID 30123094, 2018). "In treated tumor tissues we also observed decreased protein levels of cyclin D1, CDK4 and CDK6 when compared to control tumors and the IHC staining of cyclin D1 showed reduced intensity in erufosine treated as compared to untreated tumors." (PMID 29464035, 2018). "Let-7 exerts its tumor suppressor function in part by inhibiting the expression of numerous oncogenes such as MYC, RAS, YAP1, HMGA2, and CDK6 and by altering cellular bioenergetics, including glucose metabolism." (PMID 30057901, 2018). "p21WAF1/CIP1 has been proposed as an alternate tumor suppressor that inhibits cell growth and the RB pathway by blocking CDK4/CDK6 activity and RB phosphorylation through inhibiting cyclin E and CDK4 in neural progenitor cells." (PMID 28968963, 2017). "pl6 (also known as CDKN2) is a tumor suppressor gene which decelerates cell progression from G1 phase to S phase by inhibiting cyclin dependent kinases such as CDK4 and CDK6." (PMID 27429046, 2016). "The dependency of KRAS mutant tumor cell lines upon CDK6 was readily apparent (rho = −0.38), but was stronger when KRAS, HRAS, NRAS, or BRAF mutant tumor cell line models were combined as a group (rho = −0.43)." (PMID 26947069, 2016). "miR-22 acts as a tumor suppressor and induces cellular senescence by regulating cyclin-dependent kinase inhibitor 1A (CDKN1A), cyclin-dependent kinase 6 (CDK6), sirtuin 1 (SIRT1), and specificity protein 1 (Sp1)." (PMID 26927063, 2016). "The current study has demonstrated that miR-214 is a new tumor-suppressive miRNA in HCC that targets multiple cell-cycle stimulated gene (E2F2, CDK3, and CDK6) promoters." (PMID 26498144, 2016). "The decreased expression of CDK4, CDK6 which were directly inhibited by p16, along with the down-regulated expression of Cyclin D1, E2F1 and pRb confirmed the anti-tumor function of miR-877-3p was the due to p16 activation." (PMID 27429046, 2016). "Three additional groups of tumor samples were selected from normally expressed samples for both EGFR, MET and CDK6." (PMID 27329726, 2016). "A moderate to intense cytoplasmic staining of tumor cells (H score = 2 to 3) with EGFR and MET Abs, and a moderate to intense nuclear staining of tumor cells (H score = 2 to 3) with CDK6 Abs were considered to define IHC positivity." (PMID 27329726, 2016).
tumor (continued). "Our results demonstrate that miR-214 has tumor-suppressive activity in HCC through inhibition of E2F2, CDK3 and CDK6." (PMID 26498144, 2016). "It is very likely that E2F2, CDK6, and CDK3 act cooperatively to initiate or promote tumor development and progression." (PMID 26498144, 2016). "Groups of three tumor samples studied by IHC were selected from the most RNA-overexpressed samples for EGFR, MET or CDK6, respectively." (PMID 27329726, 2016). "As expected, we found that Cyclin D1 and CDK6 were downregulated in vivo by miR-211 and that EOC tumor growth was reduced significantly by miR-211 overexpression." (PMID 25889927, 2015). "We further demonstrate that normal function of this tumor suppressor microRNA is to down-regulate a number of putative oncogenes including validated miR-22 targets MAX, MYCBP, HDAC4, HDAC6, CDK6, and NCoA1." (PMID 26244872, 2015). "NEUROG1 is a transcription factor involved in neuronal development and differentiation, and CDKN2A (p16) is a tumor suppressor that inhibits cyclin-dependent kinases CDK4 and CDK6." (PMID 26157509, 2015). "In the fresh subcutaneous tumor, we detected the expression of miR-1 by RT-PCR and the expression of CDK4, CDK6, Caprin1 and Slug by Western Blot." (PMID 26036633, 2015). "For example, the restoration of miR-34a-5p, a tumor suppressive miRNA that simultaneously downregulates the expressions of MET, PDGFRA and CDK6, can possibly outperform any single targeted agents tailored to those targets." (PMID 26439688, 2015). "These include caveolin 1 [which directly binds DLC1 and contributes to its tumor suppressive roles], CDKN1B [which is an inhibitor of and directly binds to CDK6], and cyclin D1 [which forms a complex with CDK6]." (PMID 25425654, 2014). "miR-191 also displayed tumor-type specific roles in tumorigenesis, as miR-191 represses MDM4 and CDK6 expression in ovarian and thyroid follicular cancer, thereby delaying cancer progression and tumor-related death." (PMID 24603541, 2014). "Further proof that the 5qA1 amplicon was crucial for the phenotype of CB42 was illustrated by treating propagated tumors with a CDK6 inhibitor (PD0332991), which inhibited tumor growth by 75%." (PMID 25162504, 2014). "Part of the CDK6-dependent gene signature is VEGF-A, which promotes tumor angiogenesis and controls de novo formation of blood vessels." (PMID 23948297, 2013). "The authors also identified CDK6, SIRT1 and Sp1 as miR-22 targets and postulated that miR-22 act as tumor suppressor." (PMID 22538858, 2013). "miR-9 has been shown to target fibroblast growth factor receptor 1 (FGFR1) and CDK6 in ALL and caudal-type homeobox 2 (CDX2) in GC, suggesting a tumor-suppressive function." (PMID 24348513, 2013). "As we had originally determined that miR-105 was higher in normal prostate epithelial cells as compared to tumour cells, we examined the relative expression of CDK6 between normal PrEC cells and PC3 tumour cells." (PMID 23950948, 2013). "In summary, high levels of expression of the cell cycle regulatory protein CDK6 are indicative of a poor prognosis in patients with GBM, especially when expressed in tumor margins." (PMID 23594394, 2013). "Tumour suppressor CDKN2A inhibits the cyclin-dependent kinases (Cdk4 and Cdk6) that initiate the phosphorylation of the pRb." (PMID 20842131, 2010). "Five miRNAs (19b, 29a, 29b, 29c and 148a) shared 70 predicted targets, some of which (CDK6, PTEN, IGF1, FRS2, PDGFRA, PIK3R1 and MXD1) regulate cellular proliferation and tumor suppression." (PMID 20949028, 2010).